PPARG (peroxisome proliferator activated receptor gamma)
Diseases named in the same sentence as PPARG in open-access papers (continued):
Sharing a sentence is not in itself a finding about the gene and the disease.
prostate carcinoma (continued). "FABP5, whose expression is directly regulated by PPARβ/δ, binds fatty acids that serve as ligands for PPARγ and enhances prostate cancer cell proliferation." (PMID 29181019, 2017). "Previous studies have shown that Bcl-xL overexpression promotes prostate cancer cells survival which can be abolished by activating PPARγ." (PMID 29181403, 2017). "In that respect, increased levels of corepressor NCOR in prostate cancer can silence the expression of target genes and constitute a potential epigenetic lesion, which selectively distorts the actions of PPARG/PPARα." (PMID 27579030, 2016). "Further investigations showed that PPARγ up-regulated VEGF expression through acting with the PPAR-responsive elements in the promoter region of VEGF gene in prostate cancer cells." (PMID 26814431, 2016). "In an in vitro study, PPARγ agonists inhibited cell proliferation in prostate carcinomas, but the effects of PPARγ agonists in an in vivo carcinogenesis model were less well described, especially for prostate carcinogenesis." (PMID 27973395, 2016). "Recently, PPARγ agonists have been shown to inhibit cell proliferation or induce apoptosis in various cancer cell lines, including prostate carcinomas." (PMID 27973395, 2016). "Effects of PPARγ-suppression on proliferation rate, anchorage-independent growth and invasiveness of prostate cancer cells were evaluated by a proliferation assay, a soft agar assay and an invasion assay, respectively." (PMID 26814431, 2016). "The suppression of tumorigenicity of prostate cancer cells by siRNA knocking down of PPARγ was likely to be achieved through inhibiting the biological activity of VEGF." (PMID 26814431, 2016). "For example, PPARγ agonists dramatically reduced cell growth of hepatocellular carcinoma, prostate cancer, and gastric cancer via regulating the expression and blocking the oncogenic proteins." (PMID 27323819, 2016). "With regard to our data, higher PPARγ expression is correlated with shorter survival in pancreatic ductal adenocarcinoma and prostate cancer and with the onset and progression of ovarian cancer." (PMID 27401457, 2016). "Suppression of PPARγ in highly malignant prostate cancer cells produced a significant reduction (up to 53%) in their proliferation rate, invasiveness (up to 89%) and anchorage-independent growth (up to 94%) in vitro." (PMID 26814431, 2016). "Despite this, increased expression of FABP5 in prostate cancer cells increased fatty acid uptake and peroxisome proliferator-activated receptor gamma (PPARγ) expression which enhanced tumor progression." (PMID 25866768, 2015). "In the majority of prostate cancers (73%), immunoreactivity and expression of PPARγ correlated inversely with tumor size and PSA levels." (PMID 25866814, 2015). "We aimed to examine the association between PPARG Pro12Ala, NFKB1 -94 ins/del, NFKBIA -826C/T, COX-1 (50C>T), and COX-2 (-1195G>A) polymorphisms on prostate cancer risk." (PMID 26788504, 2015). "In prostate cancer patients, protective effects of PPARγ and therapeutic effect of TZDs were in line." (PMID 25866814, 2015). "n-3 PUFA can induce apoptosis in human prostate cancer cells by activating the nuclear receptor PPARγ and upregulating the PPARγ target gene, syndecan-1 (SDC-1)." (PMID 23762859, 2013). "Human prostate cancer cells have been shown to express PPARγ at prominent levels, while its expression in normal prostate tissues was very low." (PMID 22418926, 2012). "Their observations demonstrated that a combination treatment using HDAC inhibitors and PPARγ agonists inhibits invasion of prostate cancer cells in vivo, through upregulation of E-cadherin expression." (PMID 23213321, 2012). "Apart from the established metabolic actions, PPARγ has also been shown to be overexpressed in several types of human cancers, including breast, colon, bladder, and prostate cancer." (PMID 23213321, 2012).
prostate carcinoma (continued). "Recent studies have shown participation of the nuclear hormone receptor PPARγ in pathophysiology of prostate cancer and its potential in the development of improved anticancer strategies." (PMID 23213321, 2012). "Several studies have shown that PPARγ activation leads to inhibition of growth of prostate-cancer cell lines, which is accompanied by morphological changes such as prominent enlarged cytoplasmic vacuoles." (PMID 23213321, 2012). "In summary, our data indicate that troglitazone induce Erk phosphorylation in human prostate cancer cells via a PPARγ-independent signaling pathway." (PMID 22448169, 2012). "In summary, PPARγ expression is upregulated in prostate cancer and the induction of PPARγ activity provides an additional therapeutic option for treatment of prostate cancer in the near future." (PMID 23213321, 2012). "Recently, a clinical assessment of PPARγ agonists in patients with prostate carcinoma was conducted." (PMID 23213321, 2012). "This suggests that a cotreatment of HDAC inhibitors and PPARγ agonists potentiates the effects in the arrest of proliferation, increases apoptosis, and decreases the invasion potential of prostate cancer cells." (PMID 23213321, 2012). "Here, we review PPARγ as an antitumor agent and summarize the antineoplastic effects of PPARγ agonists in prostate cancer." (PMID 23213321, 2012). "For example, the PPARγ agonist prostaglandin J2 induced autophagic cell death in prostate cancer cells and the phytochemical sulforaphane induced autophagic cell death in prostate cancer cells." (PMID 21129193, 2010). "PPARG has been reported to repress prostate cancer under some undetermined mechanisms, mainly due to the disadvantage made by adipogenesis for a cell to maintain in undifferentiated state." (PMID 19640296, 2009). "In prostate,PPARγ immunoreactivity wassignificantly higher in prostate cancer and prostatic intraepithelial neoplasiathan in those with benign prostate hyperplasia and with healthy prostate." (PMID 18483618, 2008). "Prostate cancer appears to be an attractivetumor target for PPARγ agonists because cancerous prostatecells express higher levels of PPARγ compared with their normal counterparts." (PMID 18779870, 2008). "The current study investigated the response to an array of thiazolidinedione agonists and an endogenous PPARγ agonist, 15dPGJ2, in bladder and prostate carcinoma cell lines of differing metastatic potential." (PMID 16519808, 2006). "It is interesting to note here that ligand activation of PPARγ has been shown to inhibit proliferation and induce apoptosis in several cancer cells such as, breast, colon and prostate cancer cells and in various leukemic cell lines." (PMID 16405739, 2006). "Our current findings demonstrate that 15dPGJ2 and TGZ induce growth arrest in bladder and prostate carcinoma cell lines in a PPARγ-independent manner, and via distinct mechanisms." (PMID 16519808, 2006). "Although PPARγ is expressed at low levels in normal colonic and breast ductal epithelium, it is significantly increased in breast and prostate carcinoma." (PMID 15583697, 2005). "PPARγ activation resulted in apoptosis of choriocarcinoma cells, prostate carcinoma cells, leukaemic cells and gastric carcinoma." (PMID 15266333, 2004). "PPARG (Peroxisome proliferator-activated receptor gamma), a member of the nuclear receptor superfamily, has demonstrated bidirectional crosstalk with AR signaling pathways in human prostate cancer." (PMID 40458476, 2025). "PPARγ has been shown to support prostate cancer growth through its roles in fatty acid synthesis, mitochondrial biogenesis, and co-operating with androgen receptor signaling, while in triple-negative breast cancer its activity strengthens lipid metabolic networks that underlie invasive behavior." (PMID 41476922, 2025). "Furthermore, a study has shown that ABA can promote quiescence via LANCL2- and PPARγ-induced MAPK activation in prostate cancer." (PMID 41009037, 2025).
prostate carcinoma (continued). "Recently, Cladosporols, secondary metabolites purified from the fungus Cladosporium tenuissimum, have been demonstrated to display an efficient ability to control cell proliferation in human colorectal and prostate cancer cells through a PPARγ-mediated modulation of gene expression." (PMID 39199386, 2024). "Furthermore, AKR1C3 which functions as a prostaglandin F (PGF) synthase as well as its isoforms PGF2α and 11β-PGF2α are reported to induce prostate cancer development by preventing the activation of peroxisome proliferator-activated receptor gamma (PPARγ)." (PMID 39055885, 2024). "Recent in vitro studies suggest that PPARγ agonists may play a dual role in the development and progression of prostate cancer." (PMID 37560306, 2023). "Tanshinone IIA may work as a potential PPARG regulator in the progression of prostate cancer, which required further investigation." (PMID 37932808, 2023). "Similarly, in prostate cancer, overexpression of PPARγ promotes Akt3 activity, inhibits nuclear output protein CRM1, and enhances nuclear retention of PPARγ coactivator 1α (PGC1α)." (PMID 37251321, 2023). "PPARG plays an important role in biological behaviors of prostate cancer." (PMID 37932808, 2023). "Further understanding of PPARγ and novel techniques to target it, may provide therapies for advanced prostate cancer." (PMID 36510001, 2023). "Some in vitro studies suggest that excessive fatty acids may facilitate the malignant progression of prostate cancer promoted by PPARγ." (PMID 37560306, 2023). "Because in vitro studies suggest that PPARγ agonists may exert dual effects on prostate cancer, the clinical impact of the use of rosiglitazone depends on the trade-off between these dual effects of PPARγ agonists." (PMID 37560306, 2023). "PPARγ activation by rosiglitazone may also reduce the action of androgen receptor in androgen-dependent prostate cancer cells." (PMID 37560306, 2023). "While the development and growth of prostate cancer can be inhibited by PPARγ agonists, stimulation of PPARγ may also directly lead to the carcinogenicity of prostate cancer via androgen receptor-dependent or -independent pathways." (PMID 37560306, 2023). "Our study provides a novel direction to further understand the mechanism of the effects of Tanshinone IIA on prostate cancer, and further molecular biological studies need to be carried on to further investigate the molecular mechanism of Tanshinone IIA’s anti-prostate cancer effect through PPARG." (PMID 37932808, 2023). "There was weak evidence for an association of genetically proxied PPARG perturbation with an elevated risk of prostate cancer (OR 1.75 [95% CI 1.07, 2.85], p=0.02) but little evidence of association with other cancer endpoints." (PMID 37171501, 2023). "Previous study has considered the development of PPARG antagonist as anti-prostate cancer agent." (PMID 37932808, 2023). "Therefore, some scholars have identified PPARγ as an important new therapeutic target for prostate cancer." (PMID 35594510, 2022). "In addition, PPARγ antagonists were shown to inhibit the growth of bladder, breast, pancreatic, and prostate cancer cells." (PMID 36358965, 2022). "The role of PPARγ in prostate cancer is somewhat more complicated." (PMID 36175875, 2022). "The activity of PPARγ is related to the occurrence and development of prostate cancer." (PMID 35594510, 2022). "Similarly, bone marrow adipocytes promote bone metastasis formation in prostate cancer, which is, in part, mediated through the PPARγ-induced activation of fatty-acid-binding protein 4 (Fabp4)." (PMID 35954274, 2022). "PPARγ agonists have also been shown to reduce prostate cancer growth in vitro and in vivo." (PMID 36175875, 2022). "Interestingly, PPARγ plays a role in controlling inflammation, and its expression increases in advanced prostate cancer; thus, its inhibition has been proposed for prostate cancer prevention and treatment." (PMID 34209203, 2021).
prostate carcinoma (continued). "Furthermore, PPARγ expression was shown to increase with cancer grade/stage and correlate with poor survival in prostate cancer patients, suggesting that PPARγ plays an oncogenic role in prostate cancer development and progression." (PMID 31212954, 2019). "It has been suggested that SB-FI-26 is a weak agonist of PPARγ in prostate cancer cells." (PMID 31258834, 2019). "Thus, when FABP5 expression is increased, excessive amounts of fatty acids are transported into the nucleus of the prostate cancer cells, where they act as signalling molecules to stimulate their nuclear receptor PPARγ." (PMID 31258834, 2019). "In addition, PPARγ upregulated VEGF expression through the binding of PPARγ in the promoter region of VEGF in prostate cancer cells." (PMID 29599799, 2018). "Therefore androgens have the potential to regulate expression of both PPARγ isoforms within normal prostate and prostate cancers." (PMID 29181019, 2017). "However, subsequent studies have indicated that human PIN and prostate cancers express more PPARγ mRNA and protein than normal prostate epithelial cells." (PMID 29181019, 2017). "In addition, PPARγ agonist inhibitors have been shown to suppress cell growth and induce apoptosis of prostate cancer cells by both PPARγ-dependent (genomic) and - independent (non-genomic) signalling pathways." (PMID 28415688, 2017). "Additional studies are required to determine whether DHT-stimulated increases in miR-27a and/or miR-27b contribute to the DHT-mediated reductions in PPARγ mRNA within prostate cancer cell lines." (PMID 29181019, 2017). "PPARs, in particular PPARγ, is deregulated in prostate cancer, and PPARγ may also regulate AR activity." (PMID 28099154, 2017). "However, additional studies must be performed to clarify the extent to which reductions in PPARγ function contribute to AR's ability to regulate prostate cancer proliferation and metabolism." (PMID 29181019, 2017). "PPARγ isoforms are expressed in prostatic epithelial cells from normal tissue and prostate cancers." (PMID 29181019, 2017). "However, recent data from our laboratory suggest that AR activation can suppress PPARγ expression and/or activity within human prostate cancers." (PMID 29181019, 2017). "At present, it is unknown whether any of these miRNAs are also regulated by PPARγ agonists within prostate cancer cells." (PMID 29181019, 2017). "While different subtypes of PPARs may have effect on tumorigencity of different cancer types, high level of expression of PPARγ has been detected in prostate cancer and cancers of some other organs." (PMID 26814431, 2016). "Thus the malignant characteristics are closely related to the level of PPARγ and that PPARγ played an important role in tumorigenicity of the prostate cancer cells." (PMID 26814431, 2016). "In this study, we investigated and established the association of five inflammation-related genetic polymorphisms, namely, PPARG Pro12Ala, NFKB1-94 ins/del, NFKBIA-826C/T, COX-1 (50C>T), and COX-2 (-1195G>A) polymorphisms, with prostate cancer risk in a Chinese population." (PMID 26788504, 2015). "The DHA metabolites thus slow prostate cancer cell proliferation by engaging the PPARγ/syndecan-1 pathway of apoptosis and thereby may contribute to the prostate cancer-suppressing effects of not only 15-LOX but also dietary DHA." (PMID 23029040, 2012). "However, in this paper we will focus on the anticancer role of PPARγ in aspect of the prevention of prostate cancer." (PMID 23213321, 2012). "To examine the mechanism(s) underlying the metabolites’ anti-proliferative activity, we focused on PC3 cells and followed earlier studies which found that DHA inhibits prostate cancer cell proliferation by activating PPARγ to induce the expression of syndecan (SDC)-1." (PMID 23029040, 2012).
prostate carcinoma (continued). "Segawa and coworkers analyzed prostate tissue from 203 patients and found that PPARγ immunoreactivity was significantly higher in patients with prostate cancer and prostatic intraepithelial neoplasia than in those with benign prostate hyperplasia and in men with healthy prostates." (PMID 23213321, 2012). "Furthermore, MCC-555, a unique partial agonist of PPARγ as an antidiabetic drug, inhibited the growth of prostate cancer cells both in vitro and in vivo." (PMID 23213321, 2012). "Furthermore, to investigate the role of PPARγ in human prostate cancer cells, several ligands of different potency and selectivity were applied to the cell line DU145 and the cell viabilities were assessed after continuous treatment with the drugs." (PMID 23213321, 2012). "However, PPARG has high expression levels in prostate cancer cells, especially for the more undifferentiated stage." (PMID 19640296, 2009). "Removal of HDAC-mediated transcriptionalsilencing via HDAC inhibitors may allow activation of PPARγ, as suggested by in vitro and in vivostudies of combined therapy of prostate cancer with HDAC inhibitors and PPARγ agonists." (PMID 19125177, 2008). "PPARγ is expressed in human prostate cancer celllines and human prostate cancer specimens." (PMID 19125177, 2008). "Interestingly, inhibition of HER-2/neutyrosine kinase activity in a prostate cancer model prevents PPARγ degradation and thereby enhancessusceptibility to PPARγ activators such as R-etodolac." (PMID 19125177, 2008). "Moreover, endogenous and synthetic PPARγ agonists elicit notable growth inhibitory effects in vitro and in vivo (colon, breast and prostate carcinomas) and are capable of preventing metastasis." (PMID 16519808, 2006). "Although genetic deficiency of PPARγ does not alter the development of experimental prostate cancer, individual PPARγ ligands have been shown to inhibit in vitro cellular proliferation of both human bladder and prostate carcinoma cell lines." (PMID 16519808, 2006). "Similarly, in vitro studies in prostate cancer cells, which express fairly abundant PPARγ, can result in the differentiation of prostate cancer cells and downregulation of androgen-stimulated PSA production." (PMID 15583697, 2005). "Interestingly, the reduction in the synthesis of the enzymes involved in SREBP-1-mediated cholesterol biosynthesis in PC-3 prostate cancer cells suggests that the inhibition of this pathway, due to the Cladosporol–PPARγ complex action, also impedes the de novo intratumoral biosynthesis of androgens." (PMID 39199386, 2024). "Our study applied transcriptomic sequencing and computer technology to suggest that Tanshinone IIA may suppress the proliferation of prostate cancer through interacting with PPARG, providing a promising direction for further understanding the anti-prostate cancer effects of Tanshinone IIA." (PMID 37932808, 2023). "However, further analysis showed that the observed inhibition of prostate cancer growth by these compounds was mediated by PPARγ-independent mechanisms such as the inhibition of the CXCR4/CXCL12 axis, or the Bcl-xL/Bcl-2 functions or the suppression of the androgen receptor expression." (PMID 36358965, 2022). "Furthermore, PPARγ promotes prostate cancer growth via the induction of VEGF expression." (PMID 35954274, 2022). "Besides, the inhibition of the expression of PPARγ may have a preventive and therapeutic effect on prostate cancer." (PMID 35594510, 2022). "The previous study has shown that PPARG could promote metastasis in prostate cancer cells." (PMID 34490113, 2021). "Indeed, recent studies showed that PPARγ activation promoted prostate cancer progression, suggesting that PPARγ inhibition might be useful in prevention and treatment for prostate cancer." (PMID 31212954, 2019).